ODF2L (outer dense fiber of sperm tails 2 like)
Description:
Acts as a suppressor of ciliogenesis, specifically, the initiation of ciliogenesis.
Synonyms: KIAA1229
Tractability: PROTAC: ubiquitination databases record sites on it.
Gene: Protein-coding gene on chromosome 1 (86,346,824 to 86,396,342, reverse strand). Ensembl gene ENSG00000122417.
Subcellular location: Cytoplasm, cytoskeleton, microtubule organizing center, centrosome; Cytoplasm, cytoskeleton, microtubule organizing center, centrosome, centriole; Cytoplasm, cytoskeleton, microtubule organizing center, centrosome, centriolar satellite; Cytoplasm, cytoskeleton, cilium basal body; Cytoplasm, cytoskeleton, microtubule organizing center, centrosome, centriolar satellite (Isoform 1); Cytoplasm, cytoskeleton, microtubule organizing center, centrosome, centriolar satellite (Isoform 6)
Gene Ontology:
Biological process: negative regulation of cilium assembly
Cellular component: centriolar satellite; centrosome; ciliary basal body; centriole
Genetic constraint (gnomAD): Loss-of-function variants: 19 observed, 15.95 expected, observed/expected ratio (o/e) 1.19, 90% interval 0.83 to 1.72. The upper end of that interval is the gene's LOEUF score, 1.72, which puts it in group 6 of 6, group 1 being the genes least tolerant of losing a copy. Missense variants: 178 observed, 165.68 expected, observed/expected ratio (o/e) 1.07, 90% interval 0.95 to 1.22. Synonymous variants: 54 observed, 55.7 expected, observed/expected ratio (o/e) 0.97, 90% interval 0.78 to 1.22.
Homologues: Orthologues: macaque ODF2L (95% identical), chimpanzee ODF2L (92% identical), rabbit ODF2L (79% identical), mouse Odf2l (74% identical), rat Odf2l (72% identical), guinea pig ODF2L (70% identical), pig ODF2L (64% identical), tropical clawed frog odf2l (37% identical). Paralogues in human: ODF2 (29% identical).
Diseases named in the same sentence as ODF2L in open-access papers:
ODF2L is named in the same sentence as 11 diseases in open-access papers, as found by Europe PMC text mining. Sharing a sentence is not in itself a finding about the gene and the disease. The quoted sentences say what the papers report.
chronic myeloid leukemia (1 paper, 2023). "Pathogenic conditions associated with aberrant expression of ODF2L, MAST2 and KIF23 include ciliopathy, liver cancer and chronic myeloid leukemia, respectively." (PMID 37026480, 2023).
colon cancer (1 paper, 2024). "Western blot and quantitative real‐time PCR (qRT‐PCR) were used to estimate the mRNA expression of ODF2L levels in six colon cancer cell lines." (PMID 38334481, 2024). "Additionally, the ODF2L expression level was significantly increased in the aged (≤60), in overweight (BMI > 28), and in colon cancer (p < 0.05)." (PMID 38334481, 2024).
COVID-19 (1 paper, 2024). A disease caused by infection with severe acute respiratory syndrome coronavirus 2. "Based on CellChat analyses, monocytes communicated predominantly with CD4+ TEM cells positively expressing PTB markers (GBP2, TRAV1-2, and ODF2L) and COVID-19 markers (LAG3 and SLFN5) in both PTB and COVID-19." (PMID 39337460, 2024). "However, there were no significant results to indicate that GBP2, TRAV1-2, and ODF2L can be used as factors to estimate the incidence of COVID-19." (PMID 39337460, 2024).
ovarian carcinoma (1 paper, 2023). A malignant neoplasm originating from the surface ovarian epithelium. "Our finding that ODF2L was a synthetic lethal partner with WEE1 and that loss of ODF2L sensitized the response to WEE1 inhibitors in ovarian cancer indicated that ODF2L could be a promising translational target for ovarian cancer treatment." (PMID 36378528, 2023). "In this study, through a cell cycle machinery–related gene RNAi screen followed by multidisciplinary approaches, we identified outer dense fiber of sperm tails 2–like (ODF2L) as a central driver of resistance to WEE1 inhibition in ovarian cancer." (PMID 36378528, 2023). "We evaluated the in vivo therapeutic potential of targeting ODF2L in combination with a WEE1 inhibitor using the ovarian cancer ID8-Luc syngeneic mouse model we previously established." (PMID 36378528, 2023). "Targeting ODF2L using an RNAi therapeutic platform sensitizes ovarian cancer cells to WEE1 inhibitor treatment in a syngeneic mouse model." (PMID 36378528, 2023). "Taken together, these data demonstrate that ODF2L expression negatively correlated with sensitivity to WEE1 inhibition in ovarian cancer." (PMID 36378528, 2023). "Furthermore, we demonstrated the in vivo therapeutic potential of targeting ODF2L with siRNA-loaded LNPs combined with AZD1775 using the ovarian cancer ID8-Luc syngeneic mouse model." (PMID 36378528, 2023). "Moreover, data mined from the Cancer Therapeutics Response Portal (CTRP), a database reporting correlations between gene expression and drug resistance for over 800 cancer cell lines, showed that ODF2L expression most significantly positively correlated with resistance to AZD1775 in ovarian cancer." (PMID 36378528, 2023). "Combination treatment with tumor-targeted lipid nanoparticles that packaged ODF2L siRNA and AZD1775 led to the synergistic attenuation of tumor growth in the ID8 ovarian cancer syngeneic mouse model." (PMID 36378528, 2023). "We also present a promising therapeutic strategy that targets ODF2L to significantly increase the sensitivity and overcome the resistance to WEE1 inhibition in ovarian cancer." (PMID 36378528, 2023). "ODF2L was identified as the third most effective target from the primary screen and emerged as a lead hit from the secondary screen, as it sensitized cancer cells to WEE1 inhibition across ovarian cancer types." (PMID 36378528, 2023). "Moreover, after normalization by the corresponding vehicle-treated group, tumor growth under AZD1775 treatment was highly correlated with ODF2L expression in the ovarian cancer PDX, indicating a role for ODF2L in affecting the response to WEE1 inhibition in EOC." (PMID 36378528, 2023). "In addition, we found that ODF2L protein abundance did not fluctuate during the cell cycle in ovarian cancer cell lines, suggesting that ODF2L expression was possibly not regulated by the cell cycle." (PMID 36378528, 2023). "To further validate the relationship between ODF2L and the response to WEE1 inhibition in EOC, we examined the correlation of ODF2L levels, CDK1 activity, and cell viability in a panel of AZD1775-treated primary EOC cells derived from 57 tissue samples from patients with ovarian cancer." (PMID 36378528, 2023). "Interestingly, by analyzing The Cancer Genome Atlas (TCGA) ovarian carcinoma (OV) database, we noticed that, similar to the strong correlation between the levels of WEE1 and PKMYT1 and that of their substrate CDK1, the level of ODF2L also significantly correlated with that of CDK1." (PMID 36378528, 2023).
cancer (2 papers, 2014 to 2023). A tumor composed of atypical neoplastic, often pleomorphic cells that invade other tissues. "One such gene was up-regulation of MLF1 interacting protein, a gene that suppresses cancer cell progression, as well the gene for outer dense fiber of sperm tails 2-like (ODF2L), which relates to defective spermatozoa." (PMID 25346719, 2014). "Three batches of experiments were performed using primary tumor tissues from patients 1, 5, and 10 (batch 1); patients 3 and 21 (batch 2); and patients 33 and 36 (batch 3), based on the differential expression levels of ODF2L in the primary cancer cells confirmed by Western blotting." (PMID 36378528, 2023). "AZD1775 treatment resulted in a significant tumor growth delay in the PDX when using the patient cancer tissue with low ODF2L expression, but not the tissue with high ODF2L expression." (PMID 36378528, 2023). "To our knowledge, ODF2L is a scaffold protein with no commercially available inhibitor; therefore, we used the targeted RNAi therapeutic lipid nanoparticle (LNP) platform called ASSET (anchored secondary scFv enabling targeting) to specifically knock down ODF2L in ID8 cancer cells in vivo." (PMID 36378528, 2023).
tumor (2 papers, 2023 to 2024). "ODF2L knockdown caused a significant decrease in tumor growth and tumor size in mice treated with AZD1775." (PMID 36378528, 2023). "Consistently, we observed significantly increased overall survival, diminished peritoneal hemorrhagic ascites, and reduced tumor nodule numbers in the combinatorial group of ODF2L loss and AZD1775 treatment." (PMID 36378528, 2023). "Tumor Immune Estimation Resource and TISIDB databases were used for investigating the relevance between ODF2L and tumor infiltration immune cells and immunomodulators." (PMID 38334481, 2024). "In this in vivo model, we found that the expression of ODF2L was dramatically increased in tumor cells from the AZD1775-treated group, as validated by quantitative reverse transcription PCR (RT-qPCR) and immunoblotting." (PMID 36378528, 2023). "Our studies using clinical samples support that upregulation of ODF2L in primary EOC cells positively correlates with CDK1 inactivation and cell viability in vitro and predicts xenografted tumor growth in vivo under AZD1775 treatment." (PMID 36378528, 2023). "Treatment with siODF2L-LNPs successfully decreased ODF2L expression in ID8 tumors but not in the main organs, including the heart, liver, spleen, lung, and liver, resulting in both the substantial activation of CDK1 and exacerbation of DNA damage in the tumor cells when combined with AZD1775." (PMID 36378528, 2023).
ODF2L also shares sentences with these, for which no sentence is quoted: ciliopathy (1 paper); colorectal adenocarcinoma (1); colorectal cancer (1); liver cancer (1); rectal adenocarcinoma (1).